G2E3-AS1 (G2E3 antisense RNA 1)
Synonyms: CAT1647; lincPRKD
Gene: Long non-coding RNA gene on chromosome 14 (30,412,075 to 30,577,622, reverse strand). Ensembl gene ENSG00000257636.
Diseases named in the same sentence as G2E3-AS1 in open-access papers:
G2E3-AS1 is named in the same sentence as 4 diseases in open-access papers, as found by Europe PMC text mining. Sharing a sentence is not in itself a finding about the gene and the disease.
G2E3-AS1 shares sentences with these, for which no sentence is quoted: tumor (2 papers); bladder cancer (1); cancer (1); kidney cancer (1).